KRAS (KRas proto-oncogene, GTPase)
Diseases named in the same sentence as KRAS in open-access papers (continued):
Sharing a sentence is not in itself a finding about the gene and the disease.
tumor (continued). "Recent data have demonstrated an association between KRAS mutational status in the primary tumor and resistance to cetuximab and panitumumab in patients with metastatic CRC." (PMID 20020061, 2009). "KRAS mutational status in the primary tumor according to metastatic site (whole series of 230 patients)." (PMID 20020061, 2009). "Mutational analysis of KRAS is commonly performed on the primary tumor because it is often the only available tissue." (PMID 20020061, 2009). "Addition of doxycycline after tumor formation leads to complete loss of kRas expression and dramatic tumor regression and subsequent withdrawal of tetracycline restores kRas expression, resulting in tumor recurrence within 3 weeks." (PMID 19076778, 2009). "Three tumors showed two-three different KRAS mutations, which were identified using real-time PCR and verified in a separate tumor block and using pyrosequencing as a complementary method." (PMID 19832985, 2009). "MASI is frequently present in mutant EGFR and KRAS tumor cells, and is associated with increased mutant allele transcription and gene activity." (PMID 19826477, 2009). "To further analyze this finding we studied an independent series of primary tumors from patients with unresectable metastatic CRC and examined the relationship between KRAS mutational status in the primary tumor and the site of tumor metastasis." (PMID 20020061, 2009). "Using direct sequencing of DNA extracted from tumor samples, the investigators detected a KRAS mutation in 16 out of 59 (27%) patients." (PMID 19386128, 2009). "Activating mutations of KRAS appear to be an early event in OC development, but predominantly tumours of the mucinous histological subtype." (PMID 19240718, 2009). "All of these findings confirm that analysis of KRAS mutational status in the primary tumor is an adequate surrogate marker of KRAS mutational status in metastases." (PMID 20020061, 2009). "The primary tumor revealed coexisting coexistence of the KRAS mutations Gly12Cys (ΔCT value 5.4, cutoff 7.0) and Gly13Asp (ΔCT 4.8, cutoff 9.0)." (PMID 19832985, 2009). "KRAS mutational status in the primary tumor according to the metastatic site (series of 110 patients)." (PMID 20020061, 2009). "An example of this is the development of EGFR tyrosine kinase inhibitors in the management of NSCLC patients where the presence of predictive markers such as EGFR and KRAS mutations in their tumours stratifies patients to receive the appropriate treatment." (PMID 18495026, 2008). "We have shown that the relations of CIMP-high with tumor differentiation, KRAS mutation and LINE-1 hypomethylation appear to differ according to MSI status." (PMID 19002263, 2008). "Epithelial growth factor receptor (EGFR) and KRAS mutation status have been reported as predictive markers of tumour response to EGFR inhibitors." (PMID 18495026, 2008). "EGFR and KRAS mutations are predominantly mutually exclusive with very rare tumours containing both genes mutated." (PMID 18495026, 2008). "They found an average age of diagnosis 10 years older in KRAS-mutated patients and that KRAS G > A transitions were actively selected by tumours." (PMID 19516960, 2008). "Activating mutations in the three RAS genes, most frequently in KRAS, have been found in ~30% of human neoplasias and are often an early event in tumor progression." (PMID 19014680, 2008). "If this is the case, tumours arising as a result of a mutation in either KRAS or BRAF should harbour similar downstream dependencies." (PMID 19018267, 2008). "Mice with concurrent KRAS mutations and LKB1 inactivation have more aggressive tumours and a shorter survival than those with only KRAS mutant cancers." (PMID 18594528, 2008). "First, we observed that homozygous loss of LKB1 in combination with KRAS resulted in an aggressive tumour phenotype with high tumour multiplicity, short survival, and frequent metastases well above those of KRAS alone." (PMID 18728656, 2008).
tumor (continued). "For these five patients, analysis of the corresponding metastatic site showed that the KRAS mutation status was identical between the primary tumour and metastases." (PMID 17375050, 2007). "We detected a KRAS mutation by sequencing analysis of DNA extracted from tumour sample in 16 out of 59 (27%) patients." (PMID 17375050, 2007). "In the present study we had the opportunity to compare the KRAS mutational status between primary tumour and metastases in five patients whom samples were available." (PMID 17375050, 2007). "A KRAS mutation was detected in 22 out of 59 tumours and, in six cases, was missed by sequencing analysis but detected using the SNaPshot and PCR-LCR assays." (PMID 17375050, 2007). "In contrast, the second study including 30 MCRC patients reported that KRAS mutation was highly predictive of tumour resistance to cetuximab." (PMID 17375050, 2007). "We determined using SnaPshot assay the KRAS status in two to three different areas of three tumours including two with KRAS mutation." (PMID 17375050, 2007). "Tumours were screened for KRAS mutations using first direct sequencing, then two sensitive methods based on SNaPshot and PCR-ligase chain reaction (LCR) assays." (PMID 17375050, 2007). "Protruding neoplasias have a significantly higher frequency of KRAS mutation than flat neoplasias, despite the similarity of the tumour size." (PMID 16404419, 2006). "In this study, we have shown that SYTO 9 is a suitable dye for mutation scanning with HRM, as it was able to sensitively detect KRAS mutations in cell line controls and in tumour samples." (PMID 17184525, 2006). "Among these 4 cases, 3 tumours demonstrated microsatellite instability and 2 tumours harboured concurrent KRAS mutation." (PMID 15784156, 2005). "In addition to the high proliferative and invasive potential of the tumour, the oncological properties of the KRAS G12D mutation likely precipitated both the abrupt onset and recurrence of massive hemothorax." (PMID 41503246, 2026). "Overexpression of YAP1-TAZ exerts proliferative effects on various tumor mutations, which may be related to the resistance to KRAS inhibitors." (PMID 41362725, 2026). "Consequently, our second purpose is to emphasize the importance of modifiable risk factors that function as tumor promoters of initiated pancreatic cells harboring KRAS mutations." (PMID 41484057, 2026). "In addition to the high proliferative and invasive potential of the tumour, the oncological properties associated with the KRAS G12D mutation likely precipitated both the abrupt onset and recurrence of massive hemothorax." (PMID 41503246, 2026). "Although uncommon in NSCLC, KRAS focal amplification can act as an independent oncogenic driver and is linked to tumor progression and poor prognosis, while its influence on PD-1/PD-L1 inhibitor response remains unclear." (PMID 41303594, 2025). "Furthermore, it was linked to classic tumor-related pathways, including KRAS, PI3K-AKT-mTOR, and MYC, as well as cell cycle and DNA repair pathways, such as the G2M checkpoint and E2F targets." (PMID 40356980, 2025). "KRAS mutations enhanced glutamine uptake and metabolism in tumor cells through various mechanisms." (PMID 40485603, 2025). "Similarly, KRAS mutations in colorectal cancer (CRC) contribute to tumor development and are associated with poor prognosis and resistance to epidermal growth factor receptor (EGFR)-targeted therapies." (PMID 39786607, 2025).
tumor (continued). "Furthermore, inhibiting GATA2-associated signaling pathways in mice with KRAS mutant NSCLC leads to tumor regression." (PMID 41514651, 2025). "It is plausible that, in samples with lower purity, the abundance of non-tumor cells may dilute the presence of tumor-derived epithelial cells, potentially impacting the detection sensitivity for KRAS mutations." (PMID 40981070, 2025). "However, in the patients with KRAS mutations, the tumor disappeared radiologically, and the pathological response reached pCR." (PMID 40936915, 2025). "Additionally, we explored the potential of liquid biopsies, demonstrating a concordance rate of 71.4% for KRAS mutation detection in circulating tumor DNA (ctDNA) relative to tissue biopsies across cohorts." (PMID 39906959, 2025). "Similarly, mutations in the KRAS gene trigger downstream signaling pathways, such as mitogen-activated protein kinases, leading to cell growth and tumor development." (PMID 40690457, 2025). "Additionally, a decrease in the KRAS G12C variant allele frequency, as assessed through sequencing of circulating tumor DNA, was associated with response." (PMID 40303413, 2025). "Oncogenic KRAS mutations actively participate in multiple metabolic processes, including lipometabolism, glycometabolism, amino acid metabolism, and nucleotide metabolism, to meet the high biosynthetic demands and accelerate tumor cell proliferation." (PMID 41184283, 2025). "Thus, the mutation in KRAS gene leads to impairment of GTPase activity hampering other signaling pathways, including inactivation of tumor suppressor pathways." (PMID 40230862, 2025). "The primary mechanism involves reducing the phosphorylation of eukaryotic translation initiation factor 4E and decreasing c-MYC expression, which may potentially inhibit tumor recurrence and metastasis in patients with KRAS mutations in clinical settings." (PMID 40519270, 2025). "However, prognosis also depends on the tumor grade and underlying molecular alterations, such as mutations in KRAS, BRAF, and GNAS." (PMID 40746921, 2025). "Besides, most KRAS-mutant tumors are found in tobacco smokers with corresponding signatures and a high tumor mutational burden (TMB)." (PMID 40809430, 2025). "Our data above suggest that loss of WT KRAS in the context of an oncogenic KRASG12D mutant can facilitate early tumor initiation, in concordance with prior studies suggesting that under certain circumstances, WT KRAS can act as a tumor suppressor and that loss of WT KRAS can drive progression." (PMID 39412982, 2025). "Previous studies have suggested that RAS mutations may be associated with a reduced benefit from pembrolizumab in dMMR tumors, potentially explaining the persistent viable tumor despite the radiological complete response in our KRAS-mutated case." (PMID 40647530, 2025). "GBM may present mutations in genes involved in activated KRAS signaling, such as NF-1 (neurofibromin-1), indicating KRAS pathways as a potential target in this tumor." (PMID 40362343, 2025). "By modifying with iRGD, we induced BiTE-mediated inward flow of activated effector T cells, specifically targeting the KRAS G12V mutation and improving tumor tissue penetration to address the problem of limited efficacy due to insufficient effector cells infiltration." (PMID 41472736, 2025). "Importantly, further analysis of variant combinations in the tumor showed that co-occurrence of KRAS and LRP1B variants significantly improved OS (p = 0.003) and merged PFS (p = 0.008)." (PMID 40011914, 2025). "Moreover, it has been well-established that mutations in KRAS, a Ras-like GTPase, constitutively activate receptor tyrosine kinase pathways, promoting the expression of genes involved in various aspects of tumor biology." (PMID 40707783, 2025).
tumor (continued). "Additionally, KRAS mutations upregulate programmed death-ligand 1 (PD-L1) expression on tumor cells, inhibiting T-cell-mediated cytotoxicity." (PMID 40361439, 2025). "The relationship between tumor sidedness and the frequency of KRAS mutation is controversial." (PMID 40142219, 2025). "Additionally, in NSCLC the presence of G12C is associated with a higher average tumor mutational burden compared to non-G12C mutants or KRAS wild-type tumors, potentially impacting on immunotherapy sensitivity." (PMID 40940900, 2025). "Notably, reduction in tumor size (21.4%) was seen in one CPI-naïve patient (KRAS G12D mutation positive, PD-L1 CPS ≥ 1) treated at 6 mg QW with disease control lasting 59.4 weeks before progression." (PMID 40234667, 2025). "In addition to broadly regulating the KRAS-associated immune signaling, KRAS influences immune cell phenotype and function by triggering tumor metabolic pathways." (PMID 41184283, 2025). "Its underlying hypothesis posits that tumor microstructural changes and heterogeneity can be reflected through imaging, thereby offering potential for predicting KRAS status and enabling personalized treatment strategies." (PMID 41584578, 2025). "Moreover, KRAS-mutant tumors frequently harbor concurrent mutations in key tumor suppressor genes, enhancing the tumor’s ability to survive under hypoxic conditions and metabolic stress." (PMID 40724985, 2025). "Similarly, KRAS mutations in tumor cells promote glutamine metabolism by inducing the expression of glutamate oxaloacetate transaminase (GOT), contributing to the maintenance of tumor cell proliferation and survival." (PMID 41041303, 2025). "Conversely, the MICA-129 homozygous allele A/A (Met/Met) variant was related to more advanced clinical characteristics, such as increased tumor invasion depth (T3/4; P = .0261, OR = 2.10), driver gene mutation (P = .0363, OR = 2.65), and KRAS mutation (P = .0392, OR = 2.23)." (PMID 41431073, 2025). "According to the tumours’ location, KRAS mutations were equally distributed within the locations, with 33.3% of cases identified in the right colon, 33.3% of cases in the left colon, and 33.3% of cases in the rectum, while no mutations have been identified in the transverse colon tumours." (PMID 39996841, 2025). "Notably, our group identified a KRAS mutation in a pituitary macroadenoma, marking its first documentation in such a tumor type." (PMID 40362343, 2025). "We observed some correlation only between the KRAS p.G12D %mutation detected by dPCR in tumor DNA and cfDNA samples (Spearman’s rho = 0.292, p = 0.044) when a >0.1% cutoff was used for a positive reaction, but not with the >0% cutoff (Spearman’s rho = 0.230, p = 0.115)." (PMID 40943438, 2025). "A fourth potential limitation of this study is that the results are based on experiments done in colon epithelial cells, so it is uncertain whether the KRAS G12V mutation will exhibit similar signaling properties in other tumor types." (PMID 40131933, 2025). "Although the effect of acetylation at residues Lys104 and Lys147 on regulating KRAS oncogenicity is inconsistent, it is unequivocally demonstrated that inhibition or knockdown of deacetylases such as SIRT1/2 and HDAC6 reduces the mutated KRAS-mediated tumor progression." (PMID 41294676, 2025). "Moreover, our data adds important aspects to the relevance of the KRAS gene mutation spectrum for tumor progression and metastasis, which has the potential to impact future research directions and therapeutic strategies in personalized medicine." (PMID 40066744, 2025).
tumor (continued). "Additionally, tumor organoids harboring activating KRAS mutations demonstrated resistance to anti-EGFR inhibitors (cetuximab and afatinib)." (PMID 40519270, 2025). "Recent advances in the development of mutation-specific KRAS inhibitors have renewed interest in understanding the impact of KRAS mutations across different malignancies, emphasizing the need for precise characterization of KRAS-driven tumor biology to guide targeted therapies." (PMID 41375035, 2025). "Similarly, ACBI3 is a pan-KRAS PROTAC degrader active against 13 of 17 of the most common KRAS mutations; it demonstrated potent and durable inhibition of KRAS signaling in vitro and tumor regression in vivo." (PMID 40829181, 2025). "In addition, similar to KRAS c.35G>T (p.Gly12Val), c.34G>T (p.Gly12Cys) has been associated with reduced tumor-infiltrating lymphocytes and an increased tumor–stromal percentage." (PMID 40075837, 2025). "Additionally, the simultaneous occurrence of KRAS mutations with other co-mutations can also influences both KRAS functionality and tumour progress." (PMID 39820726, 2025). "In addition to gaining activating mutations in oncogenes such as KRAS, malignant tumours must also develop a microenvironment which inhibits anti-cancer immune surveillance while simultaneously facilitating tumour growth." (PMID 40890297, 2025). "Molecular testing revealed a KRAS c.35G > T (p.G12V) mutation in the tumor." (PMID 41310725, 2025). "Yet, the mechanisms linking KRAS mutations and progressive allelic imbalances to tumor formation remain unclear." (PMID 41219537, 2025). "Additionally, the mutation profiles differ, with right-sided tumors more frequently showing BRAF mutations, while left-sided tumors show higher rates of APC and KRAS mutations.5) Moreover, responses to systemic therapy vary based on tumor location." (PMID 41139484, 2025). "Consequently, both cytotoxic T-lymphocytes and memory T cells are activated against tumor cells harboring these specific KRAS mutations." (PMID 40002297, 2025). "Moreover, AMG 193 showed antitumor activity in combination with chemotherapy or with sotorasib (KRAS inhibitor active towards tumor cells with p.Gly12Cys mutation in KRAS gene) in vitro and in animal models." (PMID 41465382, 2025). "Notably, transformed tumour cells with oncogenic KRAS mutations display a greater dependency on KRAS in anchorage‐independent cultures compared with monolayer cultures." (PMID 39843398, 2025). "However, in a randomised, open-label phase II trial comparing afatinib with cetuximab in patients with mCRC, afatinib demonstrated inferior efficacy to cetuximab in KRAS wild-type tumours, and only modest disease control in KRAS-mutated tumours." (PMID 40940907, 2025). "Notably, the prevalence of high TMB (≥10 mutations/Mb) differs among KRAS mutation subtypes, correlating with an increased neoantigen load that enhances tumor immunogenicity in NSCLC." (PMID 40723270, 2025). "Additionally, studies utilizing platelets as liquid biopsy have demonstrated that mutated KRAS variants originating from various tumor types can be transferred to platelets." (PMID 40244100, 2025). "In recent years, however, evidence has emerged suggesting that fibroelastoma may indeed be a genuine neoplasm, driven by a KRAS gene mutation, a finding that opens new avenues for research." (PMID 39941213, 2025). "KRAS mutations promote tumor cell proliferation and survival by activating key signaling pathways, including the PI3K/Akt and MAPK pathways, and modulating the cellular response to chemotherapy, often by reducing drug-induced apoptosis or altering drug metabolism." (PMID 40437561, 2025).